SCARNA2 (small Cajal body-specific RNA 2)
Synonyms: mgU2-25/61; HBII-382
Gene: Small Cajal body-specific RNA gene on chromosome 1 (109,100,193 to 109,100,612, forward strand). Ensembl gene ENSG00000278249.
Gene Ontology:
Biological process: RNA processing
Cellular component: nucleolus
Homologues: Orthologues: chimpanzee SCARNA2 (99% identical), rabbit SCARNA2 (84% identical).
Diseases named in the same sentence as SCARNA2 in open-access papers:
SCARNA2 is named in the same sentence as 2 diseases in open-access papers, as found by Europe PMC text mining. Sharing a sentence is not in itself a finding about the gene and the disease. The quoted sentences say what the papers report.
breast carcinoma (1 paper, 2025). "This also supports potential tumor suppressor roles of SCARNA2 in breast cancer." (PMID 41283331, 2025).
tumor (2 papers, 2025). "Staging data supported the presumed tumor suppressor roles of SCARNA2, SNORD15B, and RNU2-1, showing their higher expression in early-stage samples compared with more advanced stages." (PMID 41283331, 2025).